B4GALT2 (beta-1,4-galactosyltransferase 2)
Description:
Responsible for the synthesis of complex-type N-linked oligosaccharides in many glycoproteins as well as the carbohydrate moieties of glycolipids. Can produce lactose.
Synonyms: Beta4Gal-T2; b4Gal-T2; B4Gal-T3
Tractability: Antibody: UniProt predicts a signal peptide or a membrane-spanning region. PROTAC: its protein half-life has been measured.
Gene: Protein-coding gene on chromosome 1 (43,978,943 to 43,991,173, forward strand). Ensembl gene ENSG00000117411.
Subcellular location: Golgi apparatus, Golgi stack membrane
Subcellular location (Human Protein Atlas): Golgi apparatus; Vesicles
Pathways (Reactome):
Metabolism: Keratan sulfate biosynthesis
Metabolism of proteins: N-Glycan antennae elongation
Gene Ontology:
Molecular function: beta-N-acetylglucosaminylglycopeptide beta-1,4-galactosyltransferase activity; lactose synthase activity; N-acetyllactosamine synthase activity; galactosyltransferase activity; glycosyltransferase activity
Biological process: carbohydrate metabolic process
Cellular component: Golgi apparatus; Golgi membrane; Golgi cisterna membrane
Genetic constraint (gnomAD): Loss-of-function variants: 18 observed, 33.91 expected, observed/expected ratio (o/e) 0.53, 90% interval 0.37 to 0.79. The upper end of that interval is the gene's LOEUF score, 0.79, which puts it in group 3 of 6, group 1 being the genes least tolerant of losing a copy. Missense variants: 404 observed, 531.23 expected, observed/expected ratio (o/e) 0.76, 90% interval 0.7 to 0.83. Synonymous variants: 214 observed, 217.27 expected, observed/expected ratio (o/e) 0.98, 90% interval 0.88 to 1.1.
Homologues: Orthologues: chimpanzee B4GALT2 (99% identical), rabbit B4GALT2 (97% identical), guinea pig B4GALT2 (97% identical), dog B4GALT2 (96% identical), pig B4GALT2 (95% identical), mouse B4galt2 (92% identical), rat B4galt2 (91% identical), macaque B4GALT2 (88% identical), tropical clawed frog b4galt2 (74% identical), zebrafish b4galt2 (70% identical), Caenorhabditis elegans bre-4 (35% identical), Drosophila melanogaster beta4GalNAcTA (31% identical). Paralogues in human: B4GALT1 (53% identical), B4GALT3 (43% identical), B4GALT4 (39% identical), B4GALT6 (35% identical), B4GALT5 (34% identical), B4GALT7 (26% identical).
Diseases named in the same sentence as B4GALT2 in open-access papers:
B4GALT2 is named in the same sentence as 14 diseases in open-access papers, as found by Europe PMC text mining. Sharing a sentence is not in itself a finding about the gene and the disease. The quoted sentences say what the papers report.
colon cancer (3 papers, 2016 to 2021). "For B4GALT2 missense mutations, have been reported in colon cancer." (PMID 30038662, 2018). "Mutation of Beta-1, 4-galactosyltransferase 2 (B4GALT2) leads to abnormal glycosylation of proteins, promoting the development of colon cancer." (PMID 34557495, 2021).
breast carcinoma (2 papers, 2019 to 2025). "Indeed, increased expression of ST8SIA4 in human leukemia and decreased expression of B4GALT2 in breast cancer cells has been associated with multidrug resistance." (PMID 30651077, 2019).
ovarian carcinoma (2 papers, 2022 to 2025). A malignant neoplasm originating from the surface ovarian epithelium. "B4GALT2, which builds key β1,4-galactosylated structures in N- and O-linked glycans, has demonstrated increased expression in ovarian cancer cells, indicating a role in tumor-associated glycosylation remodeling." (PMID 40963867, 2025).
developmental delay (1 paper, 2025). "Case 1101: Decreased expression of the B4GALT2 gene (UDP-GAL: beta-GlcNac beta-1,4-galactosyltransferase, polypeptide 2) gene was found in blood isolated from a male with profound global developmental delay, spastic quadriplegia and acute rhabdomyolysis (z-score: −3.40, FC: 0.45, p value: 8.30e−4)." (PMID 40593860, 2025).
liver cancer (1 paper, 2020). An epithelial or non-epithelial malignant neoplasm that arises from the liver. "B4GALT2, B4GALT3, DPM1, DPM2, HS2ST1, and PIGS are unfavorable prognostic markers in liver cancer according to the analysis by human protein atlas." (PMID 32850363, 2020).
lung adenocarcinoma (1 paper, 2025). A carcinoma that arises from the lung and is characterized by the presence of malignant glandular epithelial cells. "B4GALT2 has been reported to be involved in the immune exclusion process in lung adenocarcinoma, with its expression level negatively correlated with CD8+ T cell infiltration, and it may affect the immune therapy response by regulating the PD-1/PD-L1 pathway." (PMID 40963867, 2025).
osteoporosis (1 paper, 2024). A condition of reduced bone mass, with decreased cortical thickness and a decrease in the number and size of the trabeculae of cancellous bone (but normal chemical composition), resulting in increased fracture incidence. "Our study performed a comprehensive analysis of important EMGs in osteoporosis and developed a diagnosis signature consisting 5 EMGs, including B4GALT4, ADH4, ACAD11, B4GALT2, and PPP1R3C with a relative higher AUC." (PMID 38589566, 2024). "Overall, this study constructed a model that can predict the incidence of osteoporosis and identified B4GALT4, ADH4, ACAD11, B4GALT2, and PPP1R3C as potential biomarkers for osteoporosis development." (PMID 38589566, 2024). "B4GALT4, ADH4, ACAD11, B4GALT2, and PPP1R3C may be valuable biomarkers for the development of osteoporosis." (PMID 38589566, 2024). "Thus, we propose that B4GALT4, ADH4, ACAD11, B4GALT2, and PPP1R3C are involved in the development of osteoporosis, potentially by modulating metabolic pathways." (PMID 38589566, 2024).
type I diabetes (1 paper, 2023). "This gene is responsible for biosynthesis and cell membrane components, and the preliminary data obtained showed that b4galt2 presented a tendency towards downregulation in the spermatozoa of Tg(ins:nfsb-mCherry) zebrafish, particularly under transient type I diabetes conditions." (PMID 37108202, 2023).
cancer (4 papers, 2016 to 2025). A tumor composed of atypical neoplastic, often pleomorphic cells that invade other tissues. "Interestingly, certain repressed genes like B4GALT2, ELANE, CTSG, MLC1, NMP3, and SLC43A3 act as cancer suppressors, inhibiting malignant features and cancer development." (PMID 40986633, 2025). "Interestingly, central carbon metabolism in cancer (HK2, MAPK3, MYC, PFKP, PKM2, SLC16A3), galactose metabolism (B4GALT2, HK2, PFKP) and fructose and mannose metabolism (HK2, PFKFB4, PFKP) are associated with metabolism." (PMID 39924557, 2025). "However, the degree of staining in DPM1, B4GALT3, B4GALT2, and B4GALNT1 was stronger in cancer tissues than normal tissues." (PMID 35356430, 2022).
tumor (2 papers, 2022 to 2025). "Glycosyltransferases—including B3GAT3, B3GNT4, and B4GALT2—play distinct yet interconnected roles in glycan biosynthesis, which can influence tumor biology." (PMID 40963867, 2025). "In particular, B4GALT2 is also annotated to GO term of metal ion binding and its expression is dramatically reduced in tumor ZLR-08 compared to adjacent normal tissue." (PMID 35538075, 2022).
B4GALT2 also shares sentences with these, for which no sentence is quoted: Congenital disorder of glycosylation, type IId (1 paper); infection (1); leukemia (1); melanoma (1).